ABCA1 (ATP binding cassette subfamily A member 1)
Diseases named in the same sentence as ABCA1 in open-access papers (continued):
Sharing a sentence is not in itself a finding about the gene and the disease.
depression (2 papers, 2022 to 2024). "Most importantly, we found that neuron-specific knockdown of ABCA1 abolished the therapeutic effects of c-MSST on depression-like behaviors and synaptic plasticity impairment." (PMID 35479414, 2022). "Collectively, these results imply that ABCA1/ApoA1 signaling pathway in the V1 is selectively activated by c-MSST, thereby rendering resistance to depression-like behaviors and synaptic dysfunction in mice." (PMID 35479414, 2022).
exfoliation syndrome (2 papers, 2019 to 2022). An autosomal dominant disorder caused by mutations in the LOXL1 gene, encoding lysyl oxidase homolog 1. "Genotype association analysis of polymorphism rs2472493 in ABCA1 in pseudoexfoliation glaucoma." (PMID 35719397, 2022).
gallstones (2 papers, 2009 to 2021). Solid crystalline precipitates in the biliary tract, usually formed in the gallbladder, resulting in the condition of cholelithiasis. "The inverse relationship between ABCA1 by miR-148a is evident in HIV positive patients with gallstones compared to their negative counterparts as demonstrated in our study." (PMID 33757439, 2021).
geographic atrophy (2 papers, 2015 to 2018). "The T allele of rs1883025 in ABCA1 is associated with a decreased risk of intermediate drusen, large drusen, geographic atrophy (GA) and neovascularization, whereas the C allele of COL8A1 is protective of the transition from intermediate to large drusen." (PMID 25893111, 2015). "Also, several studies have demonstrated ABCA1 was significantly related to the progression of drusen, but the association between large drusen and geographic atrophy/neovascular was not significant." (PMID 29977615, 2018).
Glomerular sclerosis (2 papers, 2022 to 2025). Accumulation of scar tissue within the glomerulus. "Preclinical validation comes from animal models, where podocyte-specific Abca1 knockout exacerbates glomerulosclerosis, whereas treatment with ABCA1 agonists like cyclodextrin ameliorates DKD pathology." (PMID 41377559, 2025).
intrahepatic cholangiocarcinoma (2 papers, 2025). A carcinoma that arises from the intrahepatic bile duct epithelium in any site of the intrahepatic biliary tree. "Notably, Saikosaponin-a (SSA), a triterpenoid saponin from Radix Bupleuri, was shown to enhance chemosensitivity in intrahepatic cholangiocarcinoma by targeting the p-AKT/BCL-6/ABCA1 axis." (PMID 41181146, 2025).
liver fibrosis (2 papers, 2021 to 2023). "Evaluate ABCA1 (rs1800977) genotyping as a noninvasive predictor of liver fibrosis severity." (PMID 36444680, 2023). "Importantly, increased cholesterol accumulation in HSCs accelerates liver fibrosis, and thus enhanced efflux through ABCA1 and ABCG1 induction while reducing ACAT2 may be additional mechanisms by which Aramchol reduces HSC fibrogenesis." (PMID 34151243, 2021).
medulloblastoma (2 papers, 2013 to 2025). A malignant, invasive embryonal neoplasm arising from the cerebellum. "Further investigation showed another family member, ABCA1, was also elevated in surviving cells in these lines, as well as in early passage cultures from pediatric medulloblastoma patients." (PMID 24219920, 2013). "Conversely, in medulloblastoma, ABCA1 overexpression confers radiation resistance, likely by altering cholesterol efflux and membrane lipid composition, which could affect DNA repair and stress response pathways." (PMID 40370434, 2025). "ABCA1 and ABCG2 proteins were only expressed on a small proportion of cells within radiation naive medulloblastoma lines." (PMID 24219920, 2013).
multiple myeloma (2 papers, 2017 to 2023). "Then, ABCA1, apolipoprotein A-I (apoA-I) and BTN3A1 play a synergistic role causing myeloma cells to secrete supraphysiological levels of IPP, which eventually leads to the exhaustion of Vγ9Vδ2T cells and a decrease in cytotoxicity and other related antitumor effects." (PMID 36793048, 2023). "ZA treatment upregulated ABCA1 expression only in cells with detectable ABCA1 under baseline conditions, such as the myeloma cell line SKMM1, primary multiple myeloma cells (CD138+ MM) and bone marrow stromal cells (BMSC) derived from multiple myeloma patients." (PMID 28580927, 2017). "The participation of transcription factors such as HIF-1α in the multiple myeloma TME promotes the active function of myeloid suppressor cells and Tregs and upregulates the expression of PD-L1 and ABCA1 on the surface of tumor cells." (PMID 36793048, 2023).
ovarian tumor (2 papers, 2019 to 2023). "Increased levels of various transporters, such as ABCA1, ABCB5, and ABCC3/MRP3, have been demonstrated in ovarian tumour tissues, and an increased expression of ABCA1, ABCB1/MDR1/P-GP, and ABCG2/BCRP has been demonstrated in ovarian CSCs." (PMID 38201468, 2023). "Moreover, it has been reported that there were high levels of ABCA1, ABCB5, and ABCC3/MRP3 expressions in ovarian tumor tissues and high levels of ABCA1, ABCB1/MDR1/P-GP, and ABCG2/BCRP expression in ovarian CSCs." (PMID 31810474, 2019).
periodontitis (2 papers, 2020 to 2023). An acute or chronic inflammatory process that affects the tissues that surround and support the teeth. "These were the periodontitis risk gene ABCA1, FBN2 (fibrillin 2), and MAPK6 (mitogen-activated protein kinase 6)." (PMID 37822091, 2023). "Expression of known periodontitis risk genes CPEB1, ABCA1, and ATP6V1C1 was significantly repressed by hsa-miR-130a-3p, -144-3p, and -144-5p, respectively." (PMID 37822091, 2023).
prion disease (2 papers, 2014 to 2022). A transmissible disease that is caused by a protein that is able to induce abnormal folding of normal cellular proteins, leading to characteristic spongiform brain changes, which are associated with neuronal loss without an inflammatory response. "Furthermore, key enzymes and transporters, such as transglutaminase 1 (Tgm1) and ATP binding cassette subfamily A member 1 (ABCA1) that have been implicated in the clearance of misfolded protein, were up-regulated in murine prion disease." (PMID 36378750, 2022). "Given the importance of cholesterol in the pathogenesis of prion disease and the key role of ABCA1 in maintaining cholesterol homeostasis, we investigated the impact of prion infection on the regulation, trafficking, and function of ABCA1." (PMID 24280226, 2014). "In prion disease, when rafts are “occupied” with PrPSc, ABCA1 is dysfunctional." (PMID 24280226, 2014). "Increased abundance of ABCA1 in prion disease was confirmed in prion-infected mice." (PMID 24280226, 2014). "Second, treatment with an LXR agonist and overexpression of heterologous ABCA1, treatments that stimulate both cholesterol efflux and ABCA1 abundance, reduce PrPC to PrPSc conversion, thus warranting further consideration as an option for treatment of prion disease." (PMID 24280226, 2014). "Interestingly, prion disease specifically targets ABCA1, but affects cholesterol efflux not only to the lipid-free apoA-I, which is the preferred substrate of ABCA1, but also to HDL and lipidated apoE, which are preferred substrates for two other transporters, ABCG1 and SR-BI." (PMID 24280226, 2014).
sarcoidosis (2 papers, 2019). Sarcoidosis is a multisystemic disorder of unknown cause characterized by the formation of immune granulomas in involved organs. "Alveolar macrophages from sarcoidosis patients and mice following MWCNT instillation show diminished expression of ABCG1 and ABCA1, and the deficiency of these transporters in MWCNT-instilled mice correlates with increased alveolar macrophage lipid accumulation." (PMID 31681260, 2019). "Whereas, down-regulation of PPAR-γ, and accordingly ABCA1 and ABCG1, in macrophages from sarcoidosis patients and mice imply a decrease in the efflux of HDL cholesterol from these macrophages." (PMID 31681260, 2019).
Scott syndrome (2 papers, 2007 to 2021). Scott syndrome is an extremely rare congenital hemorrhagic disorder characterized by hemorrhagic episodes due to impaired platelet coagulant activity. "In vitro expression studies revealed that the 1925Q variant showed impaired trafficking to the plasma membrane, while wild-type ABCA1 overexpression in Scott Syndrome lymphocytes complemented the calcium-dependent PS exposure at the cell surface." (PMID 33562440, 2021).
tauopathy (2 papers, 2024). Neurodegenerative disorders involving deposition of abnormal tau protein isoforms (tau proteins) in neurons and glial cells in the brain. "Despite the paradoxical nature of the change, the upregulation of Abca1 was recently found to ameliorate neurodegeneration and neuroinflammation in a tauopathy model, suggesting potential beneficial effects of 24S-HC reduction." (PMID 38540675, 2024).
thrombotic disorders (2 papers, 2012 to 2021). "It is known that ABCA1 participates in infectious and/or thrombotic disorders involving vesiculation, and in vitro studies and animal models indicate that ABCA1 also plays an important role in MP formation." (PMID 33562440, 2021).
acute promyelocytic leukemia (1 paper, 2024). An aggressive form of acute myeloid leukemia (AML), characterized by arrest of leukocyte differentiation at the promyelocyte stage, due to a specific chromosomal translocation t(15;17) in myeloid cells. "Moreover, in the presence of M2 macrophages, the cytotoxic effect of CAR19 cells on DB cells, but not CD19-negative acute promyelocytic leukemia cells (HL60 cells), was markedly inhibited compared with that in the control cells; however, it was restored by ABCA1 knockdown." (PMID 38890370, 2024).
adenoid cystic carcinoma (1 paper, 2025). A malignant tumor arising from the epithelial cells. "We used the “pathological stage map” module of HEPIA2 to observe the correlation between ABCA1 expression and the pathological stage of cancers, such as ACC (adenoid cystic carcinoma) and BLCA (bladder urothelial carcinoma)." (PMID 40297807, 2025).
aneurysm (1 paper, 2022). Bulging or ballooning in an area of an artery secondary to arterial wall weakening. "The inverse correlation of CLC with ABCA1-CEC and CETP activity found only in AAA is again consistent with the existence of a link between accelerated HDL metabolism, intracellular cholesterol, and aneurysm formation." (PMID 36172376, 2022).
Arthritis (1 paper, 2023). Inflammation of a joint. "This suggests that ABCA1‐mediated cholesterol was restored in plaque macrophages, contributing to LXR‐induced lesion regression in arthritis." (PMID 37091327, 2023).
astrocytic tumor (1 paper, 2022). A glial tumor of the brain or spinal cord showing astrocytic differentiation. "Both LRP-1 and ABCA-1 high expression was associated with significantly shorter survival when all the astrocytic tumor cases and GBM were assessed together." (PMID 36267880, 2022). "High protein expression of LRP-1 and ABCA-1 was associated with significantly shorter survival when all the astrocytic tumors, including GBM, LGA, and HGA assessed together (Estimated mean OS for LRP-1 – 70.0 vs. 100.3 weeks; Estimated mean OS for ABCA-1– 62.3 vs. 116.2 weeks)." (PMID 36267880, 2022). "LRP-1 and ABCA-1 mRNA expression and immunohistochemical expression score in GBM (Gr 4), IDH wild type (WT) and comparison with astrocytic tumors (Gr 4), IDH Mut [HGA] and astrocytic tumors (Gr 2/3), IDH Mut [LGA]." (PMID 36267880, 2022). "Similar to LRP-1, the expression of ABCA-1 was also significantly higher in cases of all GBM and other diffusely infiltrating astrocytic tumor as compared to the normal brain." (PMID 36267880, 2022).
Atherosclerotic lesion (1 paper, 2023). A lesion associated with atherosclerosis, a multifactorial and multipart progressive disease manifested by the focal development within the arterial wall of lesions, that ranges from the development of a fatty streak, plaque progression, and plaque disruption. "It has been demonstrated that more than 50% of foam cells in human and mouse atherosclerotic lesions are SMC-derived following a decrease in the expression of ATP-binding cassette transporter A1 (ABCA1), one of the transporters responsible for cholesterol efflux." (PMID 37951959, 2023).
autism (1 paper, 2025). Persistent deficits in social interaction and communication and interaction as well as a markedly restricted repertoire of activity and interest as well as repetitive patterns of behavior.
bile duct tumor (1 paper, 2025). "Single-cell RNA-seq mapping of FLNC, MAP2K1, and ABCA1 reveals highly specific, lineage-restricted transcriptional programs within the bile duct tumor microenvironment." (PMID 41373405, 2025).
carotid atherosclerosis (1 paper, 2025). A thickening and loss of elasticity of the walls of carotid arteries that occur with formation of atherosclerotic plaques. "Correlation analysis revealed that the KLF11 levels in the aorta were positively correlated with the ABCA1 and ABCG1 levels in normal controls and carotid atherosclerosis patients, suggesting that KLF11 regulates ABCA1 and ABCG1 expression." (PMID 40397286, 2025). "Moreover, KLF11 levels in the aorta were positively correlated with the ABCA1 and ABCG1 levels in normal controls and carotid atherosclerosis patients." (PMID 40397286, 2025).
Chlamydia pneumoniae (1 paper, 2023). "Chlamydia pneumoniae (C. pneumoniae) infection decreased cholesterol efflux by downregulating expression of ABCA1 in A549 lung epithelial cell lines." (PMID 37529351, 2023).
cholelithiasis (1 paper, 2015). The presence of crystallized deposits forming in the gallbladder or biliary tree, primarily composed of cholesterol, bilirubin, and bile. "ABCA1 is expressed in gallbladder and plays a role in cholesterol concentrations in bile, and thus higher ALP and GGT levels observed in premenopausal women bearing ABCA1/R230C and consuming high carbohydrates might be related to a higher risk of cholestasis or cholelithiasis." (PMID 26579206, 2015). "Once again, although ABCA1 has not been reported as a gene associated with cholelithiasis, it might be involved in the pathogenesis of the disease in premenopausal women with certain dietary patterns." (PMID 26579206, 2015).
cholesteryl ester storage disease (1 paper, 2018). A form of lysosomal acid lipase deficiency characterized by progressive cholesterol esters and triglyceride accumulation in tissues and organs typically presenting with hepatosplenomegaly, liver dysfunction and/or dyslipidemia. "The importance of lysosomally-derived cholesterol in regulating ABCA1 expression has previously been demonstrated in the lysosomal cholesterol storage disorders Niemann Pick type C (NPC) and cholesteryl ester storage disease (CEST)." (PMID 29522534, 2018).
chronic myelogenous leukemia (1 paper, 2022). "ABCA1 mutations are associated with chronic myelogenous leukemia." (PMID 35460704, 2022).
co-infection (1 paper, 2012). "ADnefmut HIV infection did not affect the expression of ABCA-1 with either Ad-Cav-1 or Ad-GFP co-infection." (PMID 23067370, 2012). "Likewise, VSV-G pseudotyped HIV (psHIVwtNef) infection down-regulated ABCA-1 expression in MDMs, and co-infection of MDMs with psHIVwtNef and Ad-Cav-1 did not restore the reduced ABCA-1 levels." (PMID 23067370, 2012).
cognitive (1 paper, 2017). "The results demonstrate that T0 treatment significantly ameliorates cognitive deficits seen in APP/E4/Abca1+/- mice, as examined by Novel Object Recognition and Contextual Fear Conditioning paradigms." (PMID 28241068, 2017).
congenital Zika syndrome (1 paper, 2021). "We can speculate that the increased fetal accumulation of the P-gp, Bcrp and Abca1 substrates during ZIKV infection may contribute to the establishment of congenital Zika syndrome, although additional studies are clearly required to answer this important question." (PMID 34093581, 2021).
coronary stenosis (1 paper, 2019). Narrowing of the coronary artery lumen diameter.
dermatitis (1 paper, 2013). An inflammatory process affecting the skin. "A single nucleotide polymorphism screen has previously shown that patients harboring an amino acid change in ABCA1 tend to suffer radiation induced dermatitis during therapy, implying ABCA1 is a contributor to cellular radio-protection, at least in some cell types." (PMID 24219920, 2013).
diffuse large B-cell lymphoma (1 paper, 2025). "Notably, all patients with genetically altered ACC had ABCA1 amplification, whereas all patients with genetically altered COAD, diffuse large B-cell lymphoma, uterine sarcoma, THYM, KIRP, and KIRC had ABCA1 mutations." (PMID 40297807, 2025).
endometritis (1 paper, 2022). An acute or chronic, usually bacterial infectious process affecting the endometrium. "Recent studies on the underlying molecular mechanism of Se immunomodulatory action against LPS‐induced endometritis in rats have revealed that Se hampered TLR‐4 migration to lipid rafts by bringing modification in lipid rafts through cholesterol depletion via LxRα‐ABCA1 pathway regulation." (PMID 36348775, 2022).
epidermoid carcinoma (1 paper, 2021). "The first evidence for the role of ABCA1 in platinum chemotherapy resistance comes from a study that demonstrated increased ABCA1 mRNA expression in a cisplatin resistant epidermoid carcinoma cell line (KCP-4)." (PMID 35582032, 2021).
esophageal cancer (1 paper, 2026). A primary or metastatic malignant neoplasm involving the esophagus. "Notably, kidney cancer growth could be suppressed by inhibiting cholesterol esterification alone, while esophageal cancer required the additional downregulation of ABCA1, indicating varying dependence on free cholesterol clearance strategies among cancers of different primary origin." (PMID 41521893, 2026). "Furthermore, in comparison between human esophageal cancer cell lines, Snail-positive TE-8 cells exhibited higher expression of ABCA1 than Snail-negative TE-15." (PMID 41521893, 2026).
experimental autoimmune encephalomyelitis (1 paper, 2021). An autoimmune demyelinating disease of the central nervous system that is produced experimentally in animals by the injection of homogenized brain or spinal cord in Freund's adjuvant. "Of note, treatment with an ABCA1 agonist increased gene expression of enzymes involved in cholesterol biosynthesis in ASTRs, and improved clinical outcome in experimental autoimmune encephalomyelitis." (PMID 32602556, 2021).
facioscapulohumeral muscular dystrophy (1 paper, 2022). An autosomal dominant disorder affecting the skeletal muscles of the face, scapula, and upper arm. "MiR-106b has been found to regulate cellular cholesterol efflux by targeting ABCA1 in macrophages, miR-106 plays a role in various dystrophies such as facioscapulohumeral muscular dystrophy, limb-girdle muscular dystrophies, and Miyoshi myopathy." (PMID 35505302, 2022).